ETV1 (ETS variant transcription factor 1)
Diseases named in the same sentence as ETV1 in open-access papers (continued):
Sharing a sentence is not in itself a finding about the gene and the disease.
tumor (continued). "PCa tumor cells are driven by a number of oncogenic alterations including highly prevalent gene fusion events such as TMPRSS2-ERG and others involving ETS family transcription factors such as ETV1/4/51,10–12." (PMID 35013146, 2022). "Furthermore, we demonstrated that AZD4547 exhibits an anti-tumor effect on KM12(Luc) by perturbing the TRKA pathway including phosphorylation of PLC-gamma and expression of DUSP6 and ETV1." (PMID 34790577, 2021). "In particular, the ETS family transcription factor ETV1, a member of the polyoma enhancer activator 3 (PEA3) Ets transcription factors, has been shown to govern EMT, activate the stromal population, and promote tumor metastasis." (PMID 31109321, 2019). "Regardless, this implies the existence of a mechanism different from SMAD stabilization by which ETV1 overexpression could exacerbate, at least in cell culture, TGF-β signaling and its tumor suppressive function." (PMID 31160676, 2019). "Women with ETV1-negative/miR-17-5p-high tumours had the best survival relative to women with other subtypes (log-rank test, P < 0.001)." (PMID 29126392, 2017). "MDA-PCa-2b and PC3 cells were thus used as suitable models to investigate whether ETV1 and ETV4 have similar mechanistic and functional involvement in tumor biology." (PMID 25595908, 2015). "Studies in other tumor types also support an involvement of ETV1 and ETV4 in AIG, but no reference was made regarding the comparative expression of these ETS in the cell models used." (PMID 25595908, 2015). "The expression level of ETV1 in the primary tumor tissues from GIST cases 1-3, in which metastasis did not develop for more than 2 years after surgery, was clearly higher than in GIST cases 4-6, in which metastasis developed within one year after surgery." (PMID 23977394, 2013). "ERG/ETV1 gene rearrangement positive and negative tumours have been reported to have distinct chromosomal aberrations, expression signatures and morphological features, thus suggesting that they represent different PCa classes." (PMID 20104229, 2010). "The fact that this relationship can be detected in TCGA‐PRAD tumor samples, expected to better represent the heterogeneity of each molecular subtype, strongly supports that the observed regulatory interaction between EGFR/STAT3 and ETV1 is likely to persist in vivo, independently of the tumor stage." (PMID 40808640, 2025). "Our in vivo results are therefore consistent with the in vitro experiments and suggest that not only do ETV1 and ERG promote the formation of larger tumours, but that MET also participates in these effects, notably observed by the reversal of ETV1/ERG‐induced tumour progression by Capmatinib." (PMID 39374163, 2025). "Conversely, expression of the GIST lineage survival factor ETV1 did not correlate with mitotic rate or whether a tumor was metastatic (right), although the magnitude of ETV1 mRNA expression was much greater than that of ETV4." (PMID 29371979, 2017). "Our results support this hypothesis because PTEN loss was only a significant independent prognostic factor for overall survival, when analysed in the ERG/ETV1 gene non-rearranged tumours." (PMID 20104229, 2010).
cancer (86 papers, 2008 to 2026). A tumor composed of atypical neoplastic, often pleomorphic cells that invade other tissues. "The AML had overall gained 4 mutations in cancer genes: ETV1 (p.R405H, VAF 30.4%), KRAS (p.G12A, VAF 27.9%), PARP1 (c.2277 + 1G > C, VAF 7.5%), and ETV6 (p.I358M, VAF 5.3%)." (PMID 38012682, 2023). "Either mutations in or loss of CIC can promote cancer progression via upregulating the expression of PEA3 group genes (ETV1/ER81, ETV4/PEA3, and ETV5/ERM), the best characterized and reliable CIC target genes." (PMID 32042269, 2020). "Association analyses revealed strong correlations between expression levels of lincRNA H19 and GIST-related oncogene ETV1 and cancer associated miR-455-3p." (PMID 30557328, 2018). "Moreover, ETV1 was significantly associated with the infiltration of cancer-associated fibroblasts and M2 macrophages in CRC." (PMID 35860243, 2022). "The authors found that BRD32048 directly binds to ETV1, influencing both its transcriptional activity and the ETV1-driven invasion of cancer cells." (PMID 40427154, 2025). "applied genetically engineered models of mammary gland tumorigenesis to demonstrate that SUMOylation of the transcription factor Etv1 is essential for maintaining cancer stem cell functions." (PMID 40546087, 2025). "Since ZEB1 is also involved in radioresistance in different cancers, we analysed the role of ETV1 in this process." (PMID 40275610, 2025). "Although several of the identified oncogenes such as MYC, ETV1, and CCND1 have been previously linked to enhancer hijacking, we identified their novel hijacked enhancers that are cancer type specific." (PMID 39033128, 2024). "Etv1C/C mice, together with Etv1nlslacZ/nlslacZ and Etv1EST/EST mice, will be very valuable models to understand how Etv1 and its isoforms are involved in those processes in cancer studies, in addition to studying their roles in normal adult tissues." (PMID 37045597, 2023). "ETV1 is an oncogenic transcription factor and is reportedly oncogenic and metastatic in several types of human cancers." (PMID 36544484, 2022). "Among the affected genes, ETV1, CCDC6, and NCOA4 are causally implicated in cancer according to the Cancer Gene Census." (PMID 32580154, 2020). "Of these primary cancers, 75% were classified into seven subtypes, defined by either specific gene fusions of ETS transcription family members (ERG, ETV1, ETV4, and FLI1) or mutations (SPOP, FOXA1, and IDH1)." (PMID 29581876, 2018). "The ETV1 target genes are generally expressed to higher levels in OE33 cells, which is suggestive of a role for ETV1 in promoting cancer cell-specific gene expression." (PMID 28859074, 2017). "To substantiate the potential interaction between COP1 and ETV1, we performed cancer cell invasion assays and transwell assays using MDA-MB-231 cells." (PMID 25884720, 2015). "Etv1/Er81 is an established regulator of fetal neuronal development whose mis-expression leads to cancer pathogenesis in diverse tissues." (PMID 25330008, 2014). "The cancer-specific survival at 11 years for the rearranged ERG/ETV1 and normal PTEN group was 59.8% and for the rearranged ERG/ETV1 and PTEN loss group was 41.0%." (PMID 20104229, 2010). "In four cancers 3′-ETV1 exhibited fusion to 5′-C15orf21 sequences, two contained translocation to 14q13.3–14q21.1, one contained fusion to HNRPA2B1 and one contained fusion to SLC45A5/Prostein." (PMID 18594527, 2008). "The cancers containing fusion of 5′-C15orf21 to 3′-ETV1 sequences included the previously reported case containing ERG and ETV1 rearrangements in distinct cancer foci of the same prostate." (PMID 18594527, 2008). "These analyses identified ETV1 gene rearrangements in cancer from 23 patients (5.4% of all cancers)." (PMID 18594527, 2008).
cancer (continued). "It has previously been shown that extracellular vesicles derived from endothelial cells (ECEVs) induce dermal fibroblasts to express a gene signature correlated with FGF2-mediated cancer associated fibroblast (CAF) activation, under the control of transcription factor ETV1." (PMID 42124642, 2026). "High expression of ETV5, similar to ETV1, indicates advanced stage and poor prognosis of CRC patients, mainly due to correlation with increasing immune infiltration with EMT-inducing M2 macrophages and cancer-associated fibroblasts (CAFs)." (PMID 39596218, 2024). "Several genetically engineered mouse (GEM) models that overexpress ERG or ETV1 showed either minimal or no phenotype early time points, thus failing to recapitulate the cancer initiating ability of ETS translocation implicated by human genetics." (PMID 37018402, 2023). "Furthermore, ETV1 tends to be associated with immune infiltration of CRC, especially with cancer-associated fibroblasts and M2 macrophages." (PMID 35860243, 2022). "ETV1 could be upregulated by BRAFV600E/MAPK pathway activation to promote cancer invasiveness and progression." (PMID 35860243, 2022). "Moreover, binding to ETV1 directly, BRD32048 suppresses the transcriptional activity of ETV1 on the MMP1 promoter to impede cancer cell invasion and proliferation." (PMID 33585247, 2020). "Interestingly, ABCA1 and ETV1 are upregulated genes by embigin overexpression in both cancer and metabolic disease cluster." (PMID 30041429, 2018). "Thus in addition to motif presence, this data indicates that these motifs are occupied in cancer cells, and further supports the existence of combinatorial actions of ETV1 and AP1 in controlling gene expression in OAC-derived cells." (PMID 28859074, 2017). "Indeed, members of the PEA3 subfamily, ETV1, ETV4 and ETV5 have been implicated in a wide range of cancers [reviewed in 15] and ETV4 has been implicated in oesophageal adenocarcinomas." (PMID 28859074, 2017). "We focused on the matched samples and found that elevated levels of open chromatin could be found around the ETV1 binding regions in two of the cancer samples; 006-T and 005-T, with a much reduced effect in 003T where the expression of ETV1 is much lower." (PMID 28859074, 2017). "Our data suggest the possibility that redox-mediated dimerization could link Etv1/4/5 factors to the response of cancer cells to their microenvironment." (PMID 25866208, 2015). "ERG, ETV1, ETV4, ETV6, FLI1, and FEV, are implicated in the pathogenesis of several cancers." (PMID 21789226, 2011). "The largest subgroup of patients (54%), lacking both PTEN gene loss and ERG/ETV1 gene rearrangements comprised a ‘good prognosis’ population exhibiting favourable cancer-specific survival (85.5% alive at 11 years)." (PMID 20104229, 2010). "Therefore, ERG and ETV1 gene status was available from 308 of the 322 patients with a PTEN score (662 TMA cancer cores)." (PMID 20104229, 2010). "Importantly, we show that the known fusion partners, including the novel ACSL3:ETV1 fusion gene, only account for 39% of cancers with an ETV1 rearrangement and it is therefore likely that many new partner genes remain to be identified." (PMID 18594527, 2008). "Notably, the copy numbers of cancer-associated genes such as KRAS, ETV1, and SMAD2, displayed a subtype-specific increase in prevalence and magnitude along PDAC progression, highlighting the importance of matched primary and metastatic samples for uncovering such patterns." (PMID 38702773, 2024). "Mutations and loss of CIC have been reported to promote the progression of various cancers via derepression of cancer-associated CIC target genes, including polyomavirus enhancer activator 3 (PEA3) group genes (ETS variant transcription factor 1 [ETV1], ETV4, and ETV5)." (PMID 36619173, 2022). "Finally, given the prevalence of ETS motifs we asked whether there was evidence for enhanced levels of open chromatin in cancer samples at regions occupied by ETV1 in the OE33 OAC cell line." (PMID 28859074, 2017).
cancer (continued). "Etv1 target genes include hTERT and matrix metalloproteinases that may mediate cancer development." (PMID 25866208, 2015). "Therefore, loss of COP1 expression or COP1 deficiency may be an important mechanism that leads to overexpression of ETV1 in cancer, promoting tumorigenesis." (PMID 25884720, 2015). "The presence of PTEN gene loss in the absence of ERG/ETV1 gene rearrangements identified a patient population (6%) with poorer cancer-specific survival that was highly significant (HR=4.87, P<0.001 in multivariate analysis, 13.7% survival at 11 years) when compared with the ‘good prognosis’ group." (PMID 20104229, 2010). "Thus only eight of the 23 cancers with re-arranged ETV1 genes had known partners." (PMID 18594527, 2008). "To understand how Setd2 deficiency increases chromatin accessibility to induce the expression of KRAS signature, we first focused on Etv1, one of the transcription factors downstream of ERK signaling and a well-defined oncogene in multiple cancer types." (PMID 36810256, 2023). "For the LUAD network, four TFs, ETV1, ETV4, ETV6, and ELK4, were involved in the pathway called “transcriptional mis-regulation in cancer”." (PMID 35524179, 2022). "Here, we reported that variations in ETV1, ETV4, and ETV5 expression level correlated with prognosis in different types of cancer including CRC." (PMID 35860243, 2022). "Other cancer stem cell markers such as MALAT1 and NEAT1 were upregulated in PDS‐grown cells, while expression of ETV1 was downregulated in PDS‐grown cells compared to 2D‐grown cells." (PMID 33356003, 2021). "In order to explore only genes related to cancer, we selected four genes, including three that were upregulated via copy number gain (ANOS1, ETV1, and XPNPEP2) and one gene (PCDH11Y) that was downregulated via copy number loss." (PMID 33470396, 2021). "Alongside this implication, we noted that the strongest motif enriched in the combined treatment group was for ETV1, a member of the ETS family of TFs and well-known as an oncogene in several cancer types including BC." (PMID 32855526, 2020). "Of these genes, RHOJ and FSTL1 have particularly been characterized more extensively, whereas ETV1 and HAS2 are newly emerging in the cancer literature." (PMID 31109321, 2019). "In the present study, we propose that Etv1 is a nuclear transcriptional factor suppressed by the TGIF1 repressor, and Etv1 upregulation mediated by TGIF1 ablation confers to increase Has2 activity and activate the HA/CD44 cancer stemness pathway in PDAC." (PMID 31109321, 2019). "Third, the best known target genes of CIC include PEA3 group genes, ETV1/ER81, ETV4/PEA3, and ETV5/ERM, which are frequently overexpressed in several different types of cancers." (PMID 26124181, 2015). "Studies have shown that ETV1, ETV4, and ETV5 are highly expressed in a variety of cancers." (PMID 39668941, 2025). "Conversely, transduction of Ube2i knockout cells with a SUMO‐resistant form of Etv1 exclusively restores high proliferation rates, as observed in bulk nonstem cancer cells." (PMID 40546087, 2025). "The radioresistance mechanism regulated by ETV1 could involve ZEB1 whose expression is controlled by ETV1 and which is at the crossroads of EMT, metastases and resistance to therapy, including radiotherapy for many cancers." (PMID 40275610, 2025).
cancer (continued). "Our study unveils EGFR‐STAT3 as an axis of oncogenic signaling driven by overexpression of the ETS transcription factor ETV1 and provides supporting evidence for the therapeutic potential of combining EGFR and STAT3 inhibitors in targeting (prostate) carcinomas with ETV1 overexpression." (PMID 40808640, 2025). "Notably, among the 14 TFs whose binding sites were sex-dependently enriched across different cancers, eight were previously found to be enriched among sex-biased expressed genes, including SP1, ETV1, ELF1, E2F1, CREB1, CTCF, SIX2, and SOX2." (PMID 39716176, 2024). "However, genes associated with cell differentiation (EPCAM, CK8, CK18, and FOXA2), EMT (SNAI1, FOSL1, and ID1), and cancer stem cells (CD44, CD133, ETV1, MALAT1, NEAT1, and NESTIN) displayed a more varied response compared to 2D cells." (PMID 33356003, 2021). "Enrichment analysis was performed using HUGO symbols of genes recurrently hit per dataset, indicating that the pathway “Transcriptional misregulation in cancer [KEGG:05202]” was significantly more frequently hit (P = 1.6 × 10−4) within PCa due to TMPRSS2, ERG, ETV1, H3FA3, SLC45A3, and ELK4." (PMID 34891161, 2021). "Among the genes located in these regions, ETV1, CCDC6, and NCOA4 are known cancer critical genes." (PMID 32580154, 2020). "Notably, the major PEA3 group members (e.g., ETV1, ETV4, or ETV5) regulated by CIC differ among cancer cell types; the expression of ETV5 and ETV4 is most highly and significantly upregulated by CIC deficiency in PC and HCC cell lines, respectively." (PMID 32238859, 2020). "DNA methylation cluster 1 contained twice the number of hypermethylated loci in comparison with cluster 3, and the epigenetic patterns were substantially different from those of ETV1- and ETV4-rearranged cancers, which exhibit more heterogeneous methylation levels." (PMID 29581876, 2018). "As determined by cluster analysis, ETV1 and FASN were differential over-expressed in malignant prostate tissue in comparison with benign biopsies, highlighting their possible relevance as future cancer markers." (PMID 28143451, 2017). "The 308 patients were stratified into those that had an ERG or ETV1 gene rearrangement in their cancers (122 patients, 40%) and those that did not (186 patients, 60%)." (PMID 20104229, 2010). "In contrast, none of the cancers with rearrangements of the ETV1 gene exhibited fusions involving TMPRSS2 or the HERV-K retroviral sequence." (PMID 18594527, 2008). "However, as more cancers were studied, a lower percentage of TMPRSS2:ETV1 fusions were found compared to TMPRSS2:ERG fusions, suggesting that other 5′ partners might be involved." (PMID 40427154, 2025). "Nevertheless, further studies are needed to define their central role in the collaborative interaction between ETV1/ERG transcription factors and the MET receptor, but for now our results show the ETV1/ERG/MET cooperation in the expression of interesting genes involved in cancer progression." (PMID 39374163, 2025). "Moreover, SUMO conjugation of Etv1 acts as a switch between stem and nonstem cancer cell states." (PMID 40546087, 2025). "We observed a lower expression level trend of ETV1 in READ, but there was no significant expressional level difference between cancer and normal tissue in COAD." (PMID 35860243, 2022). "Furthermore, overexpression of ETV1 in benign prostate cells increased cell invasion without affecting proliferation; however, transgenic mice overexpressing ETV1 developed mouse PIN (mPIN), but not carcinoma." (PMID 40427154, 2025).